TYR (tyrosinase)
Diseases named in the same sentence as TYR in open-access papers (continued):
Sharing a sentence is not in itself a finding about the gene and the disease.
albinism (continued). "An Oriental and Colourpoint Shorthair cat pedigree segregating for albinism was analysed for association with TYR by linkage and sequence analyses." (PMID 16573534, 2006). "Although various gene mutations cause albinism, tyrosinase-dependent dopamine production may be associated with ocular phenotypes in albinism." (PMID 40591716, 2025). "On a molecular level, tyrosinase (TYR) is a key rate-limiting enzyme that catalyses the conversion of tyrosine into intermediate metabolites common to the pheomelanogenic and eumelanogenic pathways; mutations in TYR lead to albinism." (PMID 39086822, 2024). "First of all, this study demonstrates that the sequencing of whole genes, as we did here with our current diagnostic panel that contains the entirety of five major albinism genes (TYR, OCA2, SLC45A2, GPR143 and HPS1), is instrumental in identifying deep intronic splice variants in these genes." (PMID 39201349, 2024). "The TYR mutation was shown to be the cause of albinism in medaka fish." (PMID 38396851, 2024). "This has important diagnostic implications; designating the TYR p.(Ser192Tyr)/p.(Arg402Gln) haplotype as pathogenic could substantially increase the diagnostic yield by ~25–50% in albinism patient cohorts with missing heritability." (PMID 35027574, 2022). "The most frequent albinism is OCA1 caused by a mutation in TYR (MIM# 606933)." (PMID 35741834, 2022). "Our report corroborates the pathogenicity of the two common TYR polymorphisms p.(Arg402Gln) and p.(Ser192Tyr) when both are located in trans with a pathogenic TYR variant and aims to expand the phenotypic spectrum of albinism in order to increase the detection rate of the albino phenotype." (PMID 35887175, 2022). "Albinism is a rare disorder often caused by high-effect rare variants in the TYR gene." (PMID 35803923, 2022). "In tyrosinase, histidine is essential for catalytic activity, and in both tyrosinase and Tyrp1, mutations to metal-coordinating histidine residues can result in reduced activity and consequently different forms of albinism." (PMID 34638544, 2021). "Besides human and mouse, TYR mutations associated with albinism have been found in rabbits, cats, rats, ferrets, minks, donkeys, humpback whale and cattle." (PMID 32041521, 2020). "Oral nitisinone may improve melanin pigmentation in patients with the OCA-1B form of albinism due to hypomorphic mutations in the tyrosinase gene." (PMID 30674731, 2019). "Therefore, rs147546939G is substantially enriched in individuals with albinism and specifically in those with only one identified pathogenic variant in TYR (P < 0.0001)." (PMID 30679655, 2019). "In conclusion, we report a pathogenic haplotype GYGQ in TYR, which may explain 15% of individuals with albinism in our cohort." (PMID 30679655, 2019). "Loss of tyrosinase (TYR) mRNA expression prevents melanin synthesis, thereby causing albinism." (PMID 22817390, 2012). "The description of the tyrosinase gene mutation may contribute to elucidate the underlying machinery of cell pigmentation and its influence on visual system development and the functioning of other systems affected by albinism." (PMID 28476152, 2017). "Albinism was observed in 80%, 63% and 21% of the offspring of albino females crossed to three different males injected with 16 pg mRNA, which were designated as m1, m2 and m3, respectively; these results imply that the tyrosinase gene was mutated in ∼21–80% of the spermatozoa." (PMID 25661867, 2015). "Because albinism in this cross is caused by the homozygous loss of function of tyrosinase, the rate-limiting enzyme in the biosynthesis of melanin, these data suggest that tyrosinase or a linked gene might play a role in disease susceptibility." (PMID 22355249, 2012). "We focus on specific genotypes in the TYR and OCA2 genes; biallelic variants in each of these two genes are associated with albinism, a clinically and genetically heterogeneous group of conditions characterised by reduced levels of melanin pigment." (PMID 39349469, 2024).
albinism (continued). "This study demonstrates that the co-occurrence of two specific variants in the TYR and OCA2 genes significantly increases the likelihood of having albinism." (PMID 39349469, 2024). "Genes associated with albinism are involved in melanogenesis, converting tyrosine to L-DOPA (a precursor of melanin) via the enzyme tyrosinase." (PMID 37762234, 2023). "A multicentre study of 907 patients with FH found that 67% of individuals had albinism caused by variants in GPR143, OCA2, TYR and HPS1 genes, followed by 21.8% with PAX6, 6.8% with SLC38A8 and 3.5% with FRMD7 variants." (PMID 37762234, 2023). "It is recommended to seek these two rare haplotypes in the genetic data of individuals with suspected albinism who carry the TYR c.1205G>A change." (PMID 37460203, 2023). "Other diagnoses detected among Africans include albinism (GPR143 and TYR genes), Senior–Loken Syndrome (NPHP4 gene), and X-linked retinoschisis (RS1 gene)." (PMID 36836473, 2023). "The most common causative genes in non-syndromic OCA are TYR and OCA2 and HSP1 is in the syndromic albinism." (PMID 35328057, 2022). "The mean AL in individuals with TYR-associated albinism (n = 25; mean AL ± SD, 22.55 ± 2.30 mm) was significantly shorter than for those with OCA2-associated albinism (n = 17; mean AL ± SD, 23.99 ± 1.85 mm) in a simple t-test (P = 0.038)." (PMID 35704304, 2022). "Since the cloning of human tyrosinase gene in 1987, much research has been carried out on the relationship between tyrosine gene and skin color (mainly albinism) in humans and animals." (PMID 36671700, 2022). "Tyrosinase (TYR) is the rate limiting enzyme for melanin synthesis, and its gene mutation will cause albinism in animals." (PMID 36671700, 2022). "Average ALs in TYR- and OCA2-associated albinism and in GPR143-associated ocular albinism are similar to those of the reference cohorts in younger patients." (PMID 35704304, 2022). "TYR- and GPR143-associated albinism was identified as having a higher risk of shorter ALs compared to the reference population." (PMID 35704304, 2022). "Molecular studies identified seven genes linked to the OCA phenotype (TYR, OCA2, TYRP1, SLC45A2, SLC24A5, C10orf11, and DCT) and one locus (OCA5) in consanguineous and sporadic albinism." (PMID 35741834, 2022). "Significantly increased odds of a longer AL (≥26 mm) were observed for BCM and BED and also (but to a lesser extent) for TYR- and OCA2-associated albinism, as well as for RPE65- and RPGR-associated disease." (PMID 35704304, 2022). "These pigment targeted gene-based therapies will be relevant for future therapies of patients with albinism, for example, through the restoration of tyrosinase production, and will depend on accurate genetic diagnosis." (PMID 33498813, 2021). "TYR gene variation not only affects the occurrence of human albinism, but also has a significant correlation with animal coat color, body color, and meat color." (PMID 33466315, 2021). "The variation of the rabbit TYR gene (T373K) leads to alteration of the last N-glycosylation site of the TYR coding sequence, which is significantly related to rabbit albinism." (PMID 33466315, 2021). "The hypomorphic TYR coding variants p.(Ser192Tyr) and p.(Arg402Gln) are part of a pathogenic haplotype GYGQ, thought to explain up to 15% of individuals with albinism." (PMID 33808351, 2021). "Mutations in the TYR gene are related to OCA subtype 1, which is the most prevalent subtype of albinism among Europeans and Euro-descendents, and is subdivided into OCA1A and OCA1B." (PMID 32411182, 2020). "We have shown that oral nitisinone increases ocular and fur pigmentation in a mouse model of one form of albinism, OCA-1B, due to hypomorphic mutations in the Tyrosinase gene." (PMID 30674731, 2019). "When tyrosinase (TYR) was biallelically mutated with CRISPR/Cas9, typical albinism was observed in the mutant pigs, including pigment loss in the skin, hair and eyes." (PMID 34691891, 2019).
albinism (continued). "Although the candidate gene SLC45A2 is known to be involved in albinism in different species, to date in cattle only mutations in the TYR and MITF genes were reported to be associated with albinism or albinism-like phenotypes." (PMID 28982372, 2017). "As the major enzymes participated in mammals albinism, TYR, TYRP1, OCA2 and SLC45A2 also exhibited down regulation in albino pigmented P. olivaceus individuals." (PMID 28777813, 2017). "Tyrosinase is a key enzyme for melanin production whose dysfunction leads to albinism in C57BL/6J mice." (PMID 27586692, 2016). "Tyrosinase function has been studied in the context of clinically significant diseases such as albinism or vitiligo, and tyrosinase dysfunction is responsible for these depigmentation diseases." (PMID 25932370, 2015). "Tyrosinase expression rescues albinism and provides a visible, dosage-sensitive, reporter for different integration sites." (PMID 24391519, 2014). "A significant overlap in the range of phenotypes in individuals with TYR (OCA1) and OCA2 mutations was found, which makes genetic screening obligatory for the diagnosis of the type of albinism of the affected individuals." (PMID 22734612, 2012). "Since albinism interacts with retinal physiology in many ways, we are performing further experiments to investigate the candidacy of tyrosinase." (PMID 22355249, 2012). "As albino phenotypes in other species are associated with tyrosinase (TYR) mutations, TYR was proposed as a candidate gene for albinism in cats." (PMID 16573534, 2006). "Our findings suggest that albinism in P. pingi is synergistically driven by hyperactivation of ubiquitin-mediated proteolysis (which suppressed TYR/TYRP1 enzymatic activity and disrupted the pH homeostasis of melanosomes), and inhibition of calcium signaling (which impeded melanin transport)." (PMID 41227331, 2025). "However, future studies involving functional assays and larger cohorts are essential to confirm the biological impact of the p.Gln48Pro substitution, clarify its role in melanogenesis, and explore potential therapeutic strategies for TYR‐related albinism." (PMID 40860304, 2025). "To demonstrate the value of gene knockouts for investigations of eco-evolutionary hypotheses, we created tyrosinase knockout cane toads (Rhinella marina) and used them to examine potential drivers of selection against albinism." (PMID 40858255, 2025). "In the present study, we analyzed 122 heterozygous patients with albinism either by whole genome sequencing or by the use of our next-generation sequencing panel that includes the entire sequence of the TYR, OCA2, SLC45A2, GPR143 and HPS1 genes (exons, introns, flanking sequences)." (PMID 39201349, 2024). "Mutations in TYR can lead to albinism, a condition characterized by the absence of pigmentation in skin, fur, and feathers because of the inability to produce melanin." (PMID 38791725, 2024). "Previous studies have suggested that albinism-associated mutations may disrupt TYRP1 catalytic activity, interactions between TYRP1 and TYR, or intracellular transport of TYRP1." (PMID 37522525, 2023). "Molecular genetic research revealed that none of the buffaloes studied had the genotype for albinism, indicating that none of the animals had a mutation in the tyrosinase gene protein (TYR)." (PMID 37238095, 2023). "TYR (Tyrosinase) (NM_000372) was one of the first human pigmentation genes identified and characterized because mutations in this gene are related to OCA1 albinism, a group of autosomal recessive disorders characterized by reduced production of melanin." (PMID 37628655, 2023). "Novel and reported TYR, OCA2 and HPS-1 variants identified in albinism families in this study." (PMID 35328057, 2022). "Also, albeit with a lower effect size, both TYR- and OCA2-associated albinism had significantly higher odds of longer ALs." (PMID 35704304, 2022).
albinism (continued). "Indeed, mutations completely abolishing tyrosinase activity result in OCA1A, the most compromised albinism phenotype, while mutations allowing some enzyme activity result in OCA1B, a milder phenotype that permits some accumulation of melanin pigment." (PMID 35887175, 2022). "Conclusively, molecular and in silico analyses of identified mutations in TYR and SLC45A2 protein provide the pathogenicity prediction as well as structural and functional changes that are likely to confirm the contribution to pathogenesis of albinism." (PMID 32849781, 2020). "While mechanistic defects in the ability to synthesize melanin are easy to grasp, for example in albinism caused by mutated tyrosinase, the downstream effects on retinal development are not obvious." (PMID 32276449, 2020). "Noteworthy, rs147546939G is exclusively present in individuals with albinism who are either heterozygous for a TYR variant (21/58 alleles, MAF = 0.362) or mutation negative (17/94 alleles, MAF = 0.1809)." (PMID 30679655, 2019). "Some of the patients in which we have identified pathogenic variants, for example TYR for albinism, have additional phenotypes like seizures which are not explained by the observed genetic variant." (PMID 29554876, 2018). "Consequently, we used the soluble intra-melanosomal domain of tyrosinase to create albinism-related mutants, which enabled us to correlate tyrosinase enzymatic activity and mutant variant protein stability." (PMID 29870551, 2018). "This mutation leads to albinism of C57BL/6 mice because the nonfunctional tyrosinase protein causes lack of melanin synthesis." (PMID 28396487, 2017). "For example, albinism is a congenital disorder, in which the body scarcely synthesises melanin, owing to the absence of tyrosinase, whereas overactivation of tyrosinase increases melanin synthesis, which causes skin problems." (PMID 29283382, 2017). "Six probands within our cohort were found to have single TYR variant previously identified in albinism patients, but no variant in another known gene." (PMID 28667292, 2017). "The tyrosinase minigene rescues albinism and provides a dosage-dependent, visible, reporter gene." (PMID 24391519, 2014). "However, GRM5 and APBA2 lie 396 kb upstream and 1025 kb upstream of TYR and OCA2, respectively, two well-known pigmentary genes for which a complete loss-of-function causes albinism in humans and in other animals." (PMID 23555287, 2013). "Several of the ciliary body/iris signature genes were noteworthy in that their mutation can lead to albinism or hypopigmentation phenotypes, including OA1 (ocular albinism type 1), TYR and TYRP1 (oculocutaneous albinism 1A and 3, respectively), and MLPH (Griscelli syndrome)." (PMID 16168081, 2005). "Twenty-nine (30%) patients had albinism caused by variants in TYR gene, 23 (24%) had OCA2, 14 (15%) had x-linked albinism with variants in GPR143 gene, 13 (13%) had other genetically verified types of albinism and in the remaining 17 (18%) the genetic cause of albinism could not be established." (PMID 38136112, 2023). "This may be the reason why another clinical manifestation of albinism involved skin, hair, and eye pigment dilution rather than complete albinism, except for albinism caused by TYR gene mutation." (PMID 37239395, 2023). "This study provided a molecular diagnosis for five of eight people with albinism by identifying variants either in homozygosis or compound heterozygous for genes associated with OCA subtypes 1 and 4, including one novel causal mutation in the TYR gene (c.1453delG)." (PMID 32411182, 2020). "Thus, even though the frequencies of 402Q and 192Y are increased in individuals with a clinical diagnosis of albinism who are heterozygous for a pathogenic variant in TYR or whom have no identified mutation, the frequencies are far too high to be pathogenic." (PMID 30679655, 2019).
albinism (continued). "Tyrosinase is considered the key enzyme in melanogenesis initiation, as normal melanin formation does not occur without tyrosinase, and the lack of this enzyme causes albinism." (PMID 26580798, 2015). "In particular, a recessively inherited TYR-related form of the coat/skin color, oculocutaneous albinism type I (OMIA:000202–9913), and a SLC45A2-related form of coat color, albinism, oculocutaneous type IV (OMIA:001821–9913) have been reported in Brown Swiss." (PMID 40913728, 2025). "Overall, this study will contribute to further studies of disease prevention and treatment of TYR- and SLC45A2-related albinism." (PMID 32849781, 2020). "This type of albinism is divided clinically into two groups: the most severe type, OCA1A, with disrupted tyrosinase activity and melanin synthesis, or the less severe OCA1B, with residual tyrosinase activity in melanin production." (PMID 32019134, 2020). "Premature stop codons (Q493STOP and Q28STOP) would be generated by a single C-to-T conversion at the target sites in DMD and TYR, which are expected to result in Duchenne muscular dystrophy (DMD) and albinism, respectively." (PMID 31253764, 2019). "A crystal structure of TYR might help to resolve the function of the EGF-domain, give clues on how OCA1 mutations cause albinism, and not unimportantly, may much better facilitate the design of drugs specifically targeting the human enzyme than e.g. mushroom tyrosinase." (PMID 27551823, 2016). "We screened 172 patients with clinical signs of albinism for sequence variations in genes most prevalent in human OCA and OA (TYR, OCA2, and GPR143)." (PMID 21541274, 2011). "The lack of tyrosinase catalytic function hinders melanin synthesis, resulting in corresponding albinism traits in the animal’s coat and skin." (PMID 37627399, 2023). "It has been found from some studies that, unlike the TYR gene-related albinism, GPR143 gene-related albinism is more likely to be complicated with a short ocular axis." (PMID 37749571, 2023). "OCA1A (MIM# 203100) is a subtype of albinism in which a lack of tyrosinase results in the most severe clinical phenotype." (PMID 35741834, 2022). "Two other variations, c.389_391delAGA and c.1185-2A > G, also identified in the TYR gene were reported in a population study, with low MAF (<0.01) but have not previously been related as causing albinism phenotype." (PMID 32411182, 2020). "Most, if not all, forms of human albinism are the direct or indirect result of reduced tyrosinase activity in the melanosome." (PMID 30674731, 2019). "The most common cause of foveal hypoplasia is albinism, but no mutations were identified in SLC45A2, TYR, TYRP1, GPR143, OCA1, OCA2, OCA3, or OCA4." (PMID 28546991, 2017). "We present a molecular analysis of TYR, P, TYRP1, MATP and GPR143, well known candidate genes for OCA and OA1 types, in 23 (OCA-22 and OA-1) South Indian families (36 affected individuals with a positive history of albinism)." (PMID 20806075, 2010). "Autosomal recessive ocular albinism (AROA) is a term that has been used for patients with albinism with an ocular phenotype caused by mutations in TYR, OCA2, TYRP, SLC45A2, SLC24A5, or LRMDA (OCA1-7), but without a clearly defined boundary between calling a phenotype OCA or AROA." (PMID 38555393, 2024). "Homozygosity for Arg341His/Cys may not disrupt in vivo TYR expression to below the critical level that can lead to albinism phenotypes." (PMID 32728090, 2020). "In addition, retinal morphology and visual function in a murine model of albinism were rescued by L-DOPA administration without pigmentation, suggesting that tyrosinase-dependent L-DOPA and subsequent dopamine could be associated with ocular phenotypes in albinism." (PMID 40591716, 2025).